PDCD4-AS1 (PDCD4 antisense RNA 1)
Gene: Long non-coding RNA gene on chromosome 10 (110,868,890 to 110,872,366, reverse strand). Ensembl gene ENSG00000203497.
Diseases named in the same sentence as PDCD4-AS1 in open-access papers:
PDCD4-AS1 is named in the same sentence as 1 disease in open-access papers, as found by Europe PMC text mining. Sharing a sentence is not in itself a finding about the gene and the disease. The quoted sentences say what the papers report.
breast cancer (1 paper, 2021). A primary or metastatic malignant neoplasm involving the breast. "Another example is PDCD4 Antisense RNA 1 (PDCD4-AS1), a NAT affecting stability of PDCD4, which is a tumor suppressor coding gene implicated in breast cancer (BC)." (PMID 33466464, 2021).